SMURF2 (SMAD specific E3 ubiquitin protein ligase 2)
Diseases named in the same sentence as SMURF2 in open-access papers (continued):
Sharing a sentence is not in itself a finding about the gene and the disease.
oral cancer (2 papers, 2014 to 2025). "Furthermore, our research has identified SMURF2 as a promising prognostic biomarker, showing a significant association with immune cell infiltration in oral cancer." (PMID 38698292, 2025). "Examining data from the TCGA database and conducting cell experiments, we discovered that SMURF2 is significantly upregulated in oral cancer tissues." (PMID 38698292, 2025). "Our study revealed that SMURF2, as demonstrated through the analysis of various databases and cell experiments, exhibited increased expression in oral cancer." (PMID 38698292, 2025). "Out of the eight TRGs studied, SMURF2 has emerged as a promising marker with prognostic potential in oral cancer." (PMID 38698292, 2025). "The findings of DCA demonstrated that SMURF2 exhibited a favorable overall benefit and possessed the ability to forecast the overall survival of individuals diagnosed with oral cancer, both in the short and long term." (PMID 38698292, 2025). "SMURF2 was upregulated in oral cancer, as confirmed by public databases and qRT-PCR analysis." (PMID 38698292, 2025). "Furthermore, the prognostic efficacy of SMURF2 warrants validation in broader cohorts of oral cancer patients." (PMID 38698292, 2025). "SMURF2 emerged as a significant prognostic indicator for patients diagnosed with oral cancer." (PMID 38698292, 2025). "Screening of the data revealed eight TRGs (TGFB3, LTBP2, BMP2, TGFB1, ACVR1, CDK9, SLC20A1, and SMURF2) with non-zero coefficients, indicating their association with the prognosis of oral cancer patients." (PMID 38698292, 2025). "This study aims to provide a deeper understanding of the TGF-β pathway’s involvement in oral cancer, offering novel insights into the prognostic significance of TRGs and highlighting SMURF2 as a potential biomarker for prognosis and immune efficacy evaluation in oral cancer." (PMID 38698292, 2025). "Importantly, this elevated expression of SMURF2 was found to correlate with a poorer prognosis in patients with oral cancer." (PMID 38698292, 2025). "Furthermore, our findings indicated a direct correlation between elevated SMURF2 levels and decreased overall survival time in oral cancer patients." (PMID 38698292, 2025). "SMURF2 could be effective in recognizing prognosis and evaluating immune efficacy for oral cancer." (PMID 38698292, 2025).
premature aging syndrome (2 papers, 2018 to 2021). Changes in the organism associated with senescence, occurring at an accelerated rate. "Specifically, type-A lamin and its splice variant Progerin, the cause of Hutchinson Gilford progeria syndrome (HGPS), a premature aging syndrome, are degraded by the HECT-type E3 ligase Smurf2 via ubiquitin-dependent autophagy." (PMID 33629655, 2021). "Here, we identified E3 ubiquitin ligase Smurf2 as a physiological regulator of lamin A and its disease‐associated mutant form progerin (LAΔ50), whose expression underlies the development of Hutchinson‐Gilford progeria syndrome (HGPS), a devastating premature aging syndrome." (PMID 29405587, 2018).
progeria (2 papers, 2018 to 2019). "The clinical implication of this study is that SMURF2‐mediated clearance of progerin represents a potential therapeutic approach in progeria treatment." (PMID 31441992, 2019). "Remarkably, acute overexpression of Smurf2 in progeria fibroblasts was able to significantly reduce the nuclear deformability." (PMID 29405587, 2018). "Another ramification of this study is that our findings on Smurf2‐mediated proteolysis of progerin lay a foundation for evaluating the efficiency of progerin clearance by Smurf2 as a possible therapeutic approach in progeria treatment." (PMID 29405587, 2018). "Remarkably, the overexpression of Smurf2 in progeria patient fibroblasts significantly reduced the nuclear deformability in these cells." (PMID 29405587, 2018). "Regulation of progerin by SMURF2 appears to be biologically relevant since ectopic expression of SMURF2 in progeria fibroblasts is able to reduce the nuclear deformability and improve the nuclear circularity, characteristic mechanical features of progeric cells." (PMID 31441992, 2019).
prostate adenocarcinoma (2 papers, 2019 to 2022). "Next, we analyzed the expression levels and subcellular biodistribution of SMURF2 in two different sets of prostate TMAs: PR1921 and HPro-Ade96Sur-01, containing in total 287 human normal and prostate adenocarcinoma (PRAD) tissue samples." (PMID 31003445, 2019).
prostate tumor (2 papers, 2018 to 2022). "We chose breast and prostate tumor TMAs based on our results demonstrating that Smurf2 knockdown in these cells increased the expression levels of A‐lamins." (PMID 29405587, 2018). "Interestingly, another member of this family, SMURF2, appears to be downregulated in organ-confined prostate tumors compared to non-organ-confined prostate tumors." (PMID 36293239, 2022).
silicosis (2 papers, 2021 to 2022). Silicosis is a respiratory disease caused by breathing in (inhaling) silica dust. "In addition, upregulation of miR‐411‐3p inhibits the levels of Smurf2 mRNA and translation, leading to COLI and α‐SMA expression in silicosis." (PMID 34783198, 2021).
Alzheimer disease (1 paper, 2026). A progressive, neurodegenerative disease characterized by loss of function and death of nerve cells in several areas of the brain leading to loss of cognitive function such as memory and language. "In replication analyses, 21 genes showed nominal support in UK Biobank and Alzheimer's Disease Genetics Consortium (ADGC) cohorts, with eight genes (TREM2, ACADS, MFSD12, NUP210L, PIEZO2, PSEN1, SMURF2, AKAP13) supported under identical masks." (PMID 41960309, 2026).
ankylosing spondylitis (1 paper, 2024). An autoimmune chronic inflammatory disorder characterized by inflammation in the vertebral joints of the spine and sacroiliac joints. "Firstly, BMSCs from patients with ankylosing spondylitis exhibit abnormal angiogenic capabilities; increased expression of the SMAD-specific E3 ubiquitin ligase Smurf2 in BMSCs is a primary cause of this anomaly." (PMID 39211390, 2024). "Smurf2 regulates angiogenesis by promoting the ubiquitination and degradation of Pentraxin 3 (PTX3), highlighting the role of E3 ubiquitin ligases in the abnormal angiogenesis associated with ankylosing spondylitis pathology." (PMID 39211390, 2024).
asthma (1 paper, 2021). "We chose SMURF2 as a candidate target of miR-216a-3p for further investigation because it was associated with asthma progression." (PMID 34749662, 2021). "Herein, we uncovered that SMURF2 level was increased in whole blood samples of childhood asthma patients and PDGF-BB-stimulated HASMCs." (PMID 34749662, 2021). "The TUG1/miR-216a-3p/SMURF2 axis was proposed to provide a novel theoretical basis for childhood asthma treatment." (PMID 34749662, 2021). "TUG1 and SMURF2 were overexpressed and miR-216a-3p was downregulated in childhood asthma patients and PDGF-BB-stimulated HASMCs." (PMID 34749662, 2021). "The mRNA expression of SMURF2 was increased 2.71-fold in whole blood samples of childhood asthma patients relative to healthy controls." (PMID 34749662, 2021). "Moreover, miR-216a-3p abundance was negatively correlated with SMURF2 mRNA expression in childhood asthma patients." (PMID 34749662, 2021). "TUG1 downregulation inhibited PDGF-BB-induced HASMC proliferation and migration by regulating miR-216a-3p/SMURF2 axis, offering novel insight into the potential application of TUG1 for childhood asthma treatment." (PMID 34749662, 2021). "However, the regulatory mechanisms of SMURF2 in childhood asthma pathogenesis have not been thoroughly elucidated." (PMID 34749662, 2021).
autoimmune disease (1 paper, 2025). A disorder resulting from loss of function or tissue destruction of an organ or multiple organs, arising from humoral or cellular immune responses of the individual to their own tissue constituents. "Given that impaired SMURF2 expression correlates with the progression of autoimmune inflammation, SMURF2 represents a potential target for autoimmune disease treatment." (PMID 41271597, 2025).
Azoospermia (1 paper, 2022). Absence of any measurable level of sperm,whereby spermatozoa cannot be observed even after centrifugation of the semen pellet. "TRAF6 activates the NF-κB pathway while TRAF4 activates the MAPK pathway through degradation of the inhibitory protein DAZAP2 (deleted in azoospermia DAZ-associated protein 2) by Smad ubiquitin regulatory factor 2 (SMURF-2)." (PMID 36311787, 2022).
B-cell lymphomas (1 paper, 2014). "As we have found previously that ~30% of Smurf2-deficient mice develop tumor spontaneously after 12 month of age, and ~70% of tumors are B-cell lymphomas in spleen, only mice that were tumor free were used in this study." (PMID 24494704, 2014).
cerebral infarction (1 paper, 2021). An ischemic condition of the brain, producing a persistent focal neurological deficit in the area of distribution of the cerebral arteries. "TTC staining exhibited that after treatment with oe-Smurf2, cerebral infarction volume was reduced in MCAO mice, which was neutralized by overexpressing DDIT4 (p < 0.05)." (PMID 33722608, 2021). "Overexpressed Smurf2 or downregulated YY1, HIF1α, or DDIT4 reduced the volume of cerebral infarction and apoptosis in MCAO mice, while enhancing cell viability and reducing apoptosis and lactate dehydrogenase leakage in OGD-treated neurons." (PMID 33722608, 2021).
Cerebral ischemia (1 paper, 2024). Restriction of arterial blood supply to the brain associated with insufficient oxygenation to support the metabolic requirements of the tissue. "Smurf2 is another E3 ligase that can inhibit neuronal apoptosis induced by cerebral ischemia and OGD, and overexpression of Smurf2 reduces brain injury in mice subjected to MCAO." (PMID 38778460, 2024).
childhood asthma (1 paper, 2021). "Moreover, we examined TUG1, miR-216a-3p and SMURF2 expression in blood samples of patients with childhood asthma and PDGF-BB-stimulated HASMCs." (PMID 34749662, 2021). "Moreover, rescue experiments revealed that enforced expression of SMURF2 could abolish the suppressive impact of miR-216a-3p on proliferation and migration in HASMCs stimulated with PDGF-BB, suggesting that miR-216a-3p exerted its roles in childhood asthma through targeting SMURF2." (PMID 34749662, 2021).
chronic asthma (1 paper, 2025). An asthma that is characterized by the development of persistent airway inflammation and recurrent attacks of breathlessness and wheezing, which vary in severity and frequency. "In parallel, Wang and Chen found that lncRNA TUG1 promotes the proliferation and migration of airway smooth muscle cells (ASMCs) through the regulation of the miR-216a-3p/SMURF2 axis, linking it to structural airway changes seen in chronic asthma." (PMID 40806181, 2025).
chronic lung infections (1 paper, 2025). "SMURF2, an E3 ubiquitin ligase involved in the TGF-β signaling pathway and known to assist in protein degradation critical to IFN-1 antiviral signaling, was linked with P. apista, a multidrug-resistant pathogen implicated in chronic lung infections." (PMID 41417796, 2025).
diffuse gastric adenocarcinoma (1 paper, 2024). An adenocarcinoma arising from the stomach. "We found two CDH1 mutations (V832L and A324V) linked to hereditary diffuse gastric adenocarcinoma that confer binding to the WW domain of the HECT type E3 ligase SMURF2, and a R794W mutation that creates an ATG8 binding site." (PMID 39009827, 2024).
disc degeneration (1 paper, 2019). "Lastly, the TGF‐β‐induced activation of the CTGF secretory pathway in Smurf2‐expressing disc cells, a potential mechanism for disc degeneration in Col2a1‐Smurf2 transgenic mice, could also be a mechanism for disc aging/degeneration in WT mice and humans." (PMID 30828686, 2019).
ductal carcinoma (1 paper, 2014). "Similarly, tissue level expression of Smurf2 was also analyzed by western blot and it was observed that human breast IDCs (Infiltrating ductal carcinoma) showed elevated constitutive expression of Smurf2 when compared to normal counterparts." (PMID 25191523, 2014).
ductal carcinomas in situ (1 paper, 2014). "Immunohistochemical analysis showed that benign mammary epithelial cells expressed high levels of Smurf2, so did cells in ductal carcinomas in situ." (PMID 24485087, 2014).
Fibroadenoma (1 paper, 2018). A benign tumor of the breast characterized by the presence of stromal and epithelial elements. "Only 1 out of the 7 fibroadenomas (14.29%) showed an intense expression of Smurf2 whereas, the remaining 6 samples (85.72%) had only mild or moderate expression of Smurf2; the same proportion as for the 7 DCIS cases." (PMID 29534682, 2018).
invasive carcinoma (1 paper, 2014). A carcinoma that is not confined to the epithelium, and has spread to the surrounding stroma. "In samples with invasive carcinomas, Smurf2 staining was found decreased focally or sometimes diffusely, and the downregulation of Smuf2 was significantly more obvious in TNBCs compared to ER+/PR + cancers." (PMID 24485087, 2014).
kidney damage (1 paper, 2014). "After 8 weeks of treatment, 24-hour urinary microalbumin (UAlb), urinary protein/urinary creatinine (Up/Ucr) values, ALT, AST, Bcr, kidney damage, TGF-β, Smad7, fibronectin (FN), and Smurf2 were detected." (PMID 24511554, 2014).
Liddle syndrome (1 paper, 2011). A rare genetic form of low-renin hypertension characterized by hypertension associated with decreased plasma levels of potassium and aldosterone. "HECT-E3s have been linked to AS (UBE3A), Liddle's syndrome (Nedd4-I), tuberous sclerosis complex (HERCI) and cancer (Smurf2, UBE3A and EDD), suggesting the functional spectrum of these proteins." (PMID 21633703, 2011).
lymph node metastasis (1 paper, 2022). "In the univariate analysis, the primary tumor site (colon vs. rectum, right-sided colon vs. left-sided colon), lymph node metastasis, surgical margin, H factor, and Smurf2 expression were correlated with OS." (PMID 35361871, 2022). "Among these, rectal cancer, positive lymph node metastasis, surgical margin (R1 and R2), and low Smurf2 expression were identified as independent poor prognosis factors (P = 0.0019, 0.0265, 0.0410, and 0.0370, respectively; Cox proportional hazards model) in multivariate analyses." (PMID 35361871, 2022).
Myocardial fibrosis (1 paper, 2024). "Several E3 ubiquitin ligases, such as WWP2, SMURF1, and SMURF2, have been identified as key regulators in myocardial fibrosis." (PMID 39055656, 2024).
neuroblastoma (1 paper, 2013). Neuroblastoma (NB) is the most common solid, extracranial childhood tumor. "It should be noted that SMURF2 is located on 17q24.1, one of the most frequently affected regions by partial and whole chromosome gains in neuroblastoma." (PMID 23308108, 2013). "Further studies are necessary to explore the possible interaction between MYCN/MYC up regulation and SMURF2 copy number gains in neuroblastoma in relation to suppression of TGFβ signaling." (PMID 23308108, 2013).
Obesity (1 paper, 2026). Accumulation of substantial excess body fat. "In mouse studies, SMURF2 overexpression robustly promoted de novo adipogenesis, which in turn conferred resistance to high-fat diet-induced obesity and metabolic disorders." (PMID 42155611, 2026).
oral squamous cell carcinoma (1 paper, 2025). "The results from Kaplan-Meier analysis indicated a significant correlation between increased SMURF2 expression and decreased overall survival in patients with oral squamous cell carcinoma." (PMID 38698292, 2025).
ovarian tumor (1 paper, 2023). "Previous studies have shown that RACK1 is a powerful tumor-promoting factor in OC, so we investigated whether SMURF2 inhibited the occurrence of ovarian tumors by regulating RACK1." (PMID 37828084, 2023). "Given that abnormally low SMURF2 expression is responsible for elevated RACK1 levels and ovarian tumor progression, our results suggest that targeting RACK1 in patients with abnormally low SMURF2 expression may be a viable stratified treatment approach." (PMID 37828084, 2023).
periodontitis (1 paper, 2021). An acute or chronic inflammatory process that affects the tissues that surround and support the teeth. "For instance, in our PPI network we found that Smad ubiquitination regulatory factor-2 (SMURF2), an ubiquitin E3 ligase responsible for proteasome-mediated degradation of enhancer of zeste homolog 2 EZH2 which is a process required for neuron differentiation is present in periodontitis." (PMID 34065604, 2021).
peripheral T-cell lymphoma (1 paper, 2014). "Among candidate molecules involved in these partially unknown events we identified by in silico analysis a transcription regulator, ZBTB44 which appears expressed in peripheral T-cell lymphoma and interacts with SMAD pathway protein like SMURF2 mediating resistance to MAPK pathway inhibitors." (PMID 25437182, 2014).
Peritoneal Fibrosis (1 paper, 2015). Disorder characterized by a wide range of structural changes in PERITONEUM, resulting from fibrogenic or inflammatory processes. "We demonstrated that Akt modulates TGF-β1-induced MMT and peritoneal fibrosis in PD via downstream interactive signaling molecules, such as, Smurf2 and Smad7, and USP4 and TβR-1." (PMID 25885904, 2015). "Thus, we hypothesized that activation of Akt by TGF-β1 increases Smurf2 expression which would inhibit Smad7, and thus Akt could participate in TGF-β1-induced MMT and peritoneal fibrosis in mice undergoing PD." (PMID 25885904, 2015).
schizophrenia (1 paper, 2024). A major psychotic disorder characterized by abnormalities in the perception or expression of reality. "The HHAC gene was related to MDD in only one paper in the literature in patients with schizophrenia, suggesting that MDD may be an atypical form of schizophrenia, while SMURF2 has not previously been reported as an MDD-related gene." (PMID 39457478, 2024).